CFTR (CF transmembrane conductance regulator)
Diseases named in the same sentence as CFTR in open-access papers (continued):
Sharing a sentence is not in itself a finding about the gene and the disease.
asthma (53 papers, 2005 to 2026). "In a multicenter study involving asthmatic patients, genetic polymorphisms in CFTR were more common in patients with severe asthma and hypersecretion." (PMID 39664985, 2024). "A total of 17 studies that examined the association of CFTR mutation heterozygosity with asthma development were included in this systematic review." (PMID 36983403, 2023). "They observed that a significant number of these patients had polymorphisms in the CFTR gene, and these mutations coincided with more severe asthma and poorer clinical control." (PMID 37841931, 2023). "Conversely, eight studies reported a positive association between CFTR mutation heterozygosity and asthma development." (PMID 36983403, 2023). "We cannot draw a definite conclusion on the association between CFTR heterozygosity and asthma development." (PMID 36983403, 2023). "Various genes have been implicated as potential risk factors in the development of asthma; among them is cystic fibrosis transmembrane conductance regulator (CFTR) gene." (PMID 36983403, 2023). "Our review revealed an apparent contradiction among studies’ results regarding the relationship between CFTR mutation heterozygosity and asthma risk." (PMID 36983403, 2023). "Various genes have been implicated in the development of asthma; among them is cystic fibrosis transmembrane conductance regulator (CFTR) gene." (PMID 36983403, 2023). "A strength of the present study is the systematic literature search of recently published studies regarding the association of CFTR heterozygosity and asthma development, which provides updated feedback on this particular topic." (PMID 36983403, 2023). "In this systematic review, we examined the association of CFTR mutation heterozygosity with asthma development." (PMID 36983403, 2023). "The aim of this systematic review was to investigate the association of CFTR mutation heterozygosity with the development of asthma, by updating the existing data with recent studies’ findings." (PMID 36983403, 2023). "One potential cause of increased susceptibility to airway infections in asthma patients is cystic fibrosis transmembrane conductance regulator (CFTR) hypofunction due to heterozygosity for a damaging CFTR mutation." (PMID 35668512, 2022). "Several chronic lung diseases, including asthma, pulmonary hypertension, and pulmonary fibrosis, however, have been linked to CFTR dysfunction as well as elevated lung tissue S1P levels that accompany airway remodeling and inflammation." (PMID 35055052, 2022). "(ii) A polymorphism in the 3′ UTR of SLC26A9 that functions as CFTR-regulated chloride-bicarbonate exchanger or chloride channel is associated with reduced protein expression and an increased risk for asthma." (PMID 27382190, 2016). "Although there is evidence, some of it conflicting, that the risk of asthma is higher in non‐CF individuals with CFTR gene variants (i.e., CFTR carrier heterozygosity), the data suggests that genetic variants are unlikely to be a dominant causal factor in non‐eosinophilic asthma." (PMID 39358991, 2025). "Various immune factors, such as atopy and specific immunogenic human leukocyte antigen (HLA) types in asthma patients, as well as genetic factors like mutations in the CF transmembrane conductance regulator (CFTR) gene in CF patients, elevate the susceptibility to ABPA in these populations." (PMID 39156318, 2024). "However, there was a lack of crucial information by some studies regarding the way asthma was diagnosed, the age of participants, or the examined CFTR mutations highlighting their methodological bias." (PMID 36983403, 2023). "Carriers for CFTR mutations have been estimated as up to 1.9% of asthma in Asians and 1.6% of asthma in Europeans, indicating the significant CF heterozygosity’s contribution to asthma cases among Asian and European populations, according to meta-analysis findings." (PMID 36983403, 2023).
asthma (continued). "Consequently, more extensive research is needed through high-quality studies to provide valid evidence and highlight the clinical benefits of identifying CFTR mutations in asthma patients, their impact on asthma severity, or treatment perspectives." (PMID 36983403, 2023). "There were 75 patients referred with physician-diagnosed asthma who had CFTR mutation testing." (PMID 35668512, 2022). "Sixth, since CFTR mutation analysis was obtained only in patients with recurrent neutrophilic bronchitis, this analysis is limited to those patients with patients referred for asthma who have infective exacerbations." (PMID 35668512, 2022). "However, it is important to consider CFTR mutations even in older patients presenting later in life with exacerbations of asthma associated with recurrent airway infections." (PMID 35668512, 2022). "In summary, CF carriers are significantly overrepresented in a cohort of asthma patients with recurrent airway infections referred to a tertiary care centre, and we recommend testing for CFTR mutations in patients with asthma with recurrent airway infections, even in older patients." (PMID 35668512, 2022). "Our study reflects that asthma associated with airway mucus hypersecretion may be linked to an intronic CFTR gene polymorphism (NM_000492.3 (CFTR): c.1680-870T>A)." (PMID 34086689, 2021). "Polymorphisms associated with the CFTR gene according to asthma severity." (PMID 34086689, 2021). "In addition, CFTR heterozygosity has been linked with recurrent airway infections in severe asthma." (PMID 36983403, 2023). "Genetic variants of CFTR gene may be possibly associated with certain asthma phenotypes." (PMID 36983403, 2023). "Additionally, CFTR mutations have probably been linked to asthma severity." (PMID 36983403, 2023). "Therefore, more extensive research, through high-quality studies, is needed in order to validate evidence in this field and to highlight the clinical benefits of identifying CFTR mutations in asthma patients, their impact on asthma severity, or treatment perspectives." (PMID 36983403, 2023). "CFTR mutation heterozygosity might influence the clinical expression of asthma." (PMID 36983403, 2023). "In addition, both 5T homozygotes showed evidence of asthma supporting the hypothesis that CFTR variations may be associated with asthma." (PMID 16212675, 2005). "This suggests a role for dysfunction in the CFTR pathway applicable to other chronic neutrophil‐dominant airways diseases, including subtypes of asthma." (PMID 39358991, 2025). "We demonstrate reduced CFTR function, CFTR protein‐expressing cells and airway ionocytes in non‐eosinophilic severe asthma in the setting of a Type 1/Type 17 cytokine environment." (PMID 39358991, 2025). "Expression of known ionocyte markers FOXI1, ASCL3, PDE1C, TFCP2L1 and CFTR in single cells was lost in hBECs from patients with neutrophilic asthma (and reduced in paucigranulocytic asthma) compared to healthy donors or eosinophilic asthma." (PMID 39358991, 2025). "Results revealed a significant reduction (~50%) in CFTR function and anion transport in non‐eosinophilic asthma hBECs." (PMID 39358991, 2025). "To further investigate ionocyte CFTR expression in asthma, we analyzed previously published single-cell RNA sequencing (scRNA-Seq) data obtained from lower-airway biopsies of asthma patients or controls." (PMID 39255033, 2024). "In contrast, ionocytes from people with asthma appeared as 2 populations: one population expressed CFTR mRNA at levels comparable to controls, while the other population of ionocytes lacked CFTR mRNA." (PMID 39255033, 2024). "This suggests a potential positive correlation between severe asthma and genetic alterations in CFTR." (PMID 37841931, 2023). "Sleep efficiency is influenced by oxygen saturation and other variables such as comorbidities (nocturnal cough, asthma, CFTR-related disorders)." (PMID 36833376, 2023).
asthma (continued). "A recent study from adult asthmatics found a higher frequency of single nucleotide polymorphisms (SNPs) in the CFTR gene among ABPA, complicating asthma compared to asthmatics and healthy controls." (PMID 36900068, 2023). "Slc26a4/pendrin regulates HCO3- efflux following cytokine stimulation, which enhances Cl- secretion via CFTR, thereby impacting fluid and mucus homeostasis and was found upregulated in asthma and COPD15,16." (PMID 35842487, 2022). "Further studies are needed to establish if this is due to insufficient CFTR correction or to epigenetic changes in CF that require more time or different signals to reduce inflammation, as has been extensively documented for asthma and COPD." (PMID 33613309, 2021). "Although the link between CFTR and asthma is still controversial, it is now well established that COPD shares some common features with CF, including bronchiectasis, mucus plugging, and inflammation." (PMID 27714410, 2017). "The lack of an association with the prevalence of chronic bronchitis stand in contrast to studies in asthma where in a Swedish cohort of asthmatics, F508del CFTR heterozygosity was significantly more prevalent when compared to the control population." (PMID 24517344, 2014). "As has been reported previously in childhood asthma, tracking of lung function abnormalities in CF commences early in life, and is considerably influenced by the CFTR genotype." (PMID 17137500, 2006). "Future studies will be necessary to determine whether ionocytes have a role in mediating airway ion transport homeostasis and regulating airway pH, other than through the CFTR, and how this impacts asthma pathogenesis in these models." (PMID 39358991, 2025). "Recent studies revealed that CFTR dysfunction induced the intracellular hyperchloride and mucus accumulation, led to persistent inflammation and airway obstruction, and finally resulted in airway hyperresponsiveness in asthma model 19-21." (PMID 39113893, 2024). "Furthermore, clinical studies have suggested a potential link between CFTR dysfunction and asthma severity." (PMID 39664985, 2024). "CFTR gene and its role in asthma development has been studied extensively over the past few years." (PMID 36983403, 2023). "Nine of them supported a lack of relationship between CFTR mutation heterozygosity and asthma susceptibility, and eight reported a positive association." (PMID 36983403, 2023). "Individuals who are heterozygous for CFTR mutations but do not develop cystic fibrosis symptoms, known as carriers, have been found to have an increased risk of developing asthma." (PMID 37841931, 2023). "Main polymorphisms associated with the CFTR gene in patients with asthma with and without airway mucus hypersecretion." (PMID 34086689, 2021). "In addition to CFTR, the involvement of anion transport in the pathophysiology of asthma is suggested by aberrant expression of other epithelial anion transporters." (PMID 27382190, 2016). "In non-CF studies, e.g., in patients with asthma, CFTR variants were associated with ABPA." (PMID 39997410, 2025). "Consequently, the relations between CFTR and asthma are still unclear." (PMID 39113893, 2024). "However, a systematic review revealed that the CFTR mutation had no significant relation with asthma susceptibility." (PMID 39113893, 2024). "In addition to recurrent infections, CFTR hypofunction may also contribute to asthma by increasing airway smooth muscle contractility by modulating cellular calcium mobilization." (PMID 35668512, 2022). "The present results support a role of SLC26A9 for airway chloride secretion in asthma, which may not be detectable in airways of CF-patients carrying the F508del-CFTR allele." (PMID 35328418, 2022). "As we did not observe changes in asthma, the imbalance observed in CF could be due to impaired host defense mechanisms associated with CFTR dysfunction in the airways, changes in regional growth condition in the lungs, and/or CF-specific antibiotic regimen." (PMID 29445257, 2017).
asthma (continued). "Ionocytes through their high expression of CFTR are established to regulate CFTR anion transport, therefore we assessed whether there was a correlation between ionocyte numbers in patients with severe non‐eosinophilic asthma plus controls compared to CFTR ion currents." (PMID 39358991, 2025). "In the OVA-induced asthma model, we also found that Suramin or PM2.5 exposures increased the expression levels of P2Y2R and CFTR, and ATP treatment reduced the P2Y2R and CFTR expressions." (PMID 39113893, 2024). "While not a treatment for ABPA, CFTR modulator therapies have been proposed to have an impact on decreasing ABPA exacerbations due to their disease-modifying effect on other acquired CFTR dysfunction diseases such as COPD and asthma." (PMID 39330416, 2024). "Several clinical trials of inhaled RNA therapy have been initiated including delivery of siRNAs for asthma (Excellair) and RSV infection (ALN-RSV01), full CFTR mRNA delivery for CF (MRT5005) and an antisense oligo also for CF (Eluforsen)." (PMID 36074947, 2022). "Non-clinical studies have characterized the involvement of CFTR in asthma, citing data obtained from human airway tissues." (PMID 37841931, 2023). "Despite on these evidences, there are still aspects of the CFTR-asthma correlation that remain not fully elucidated, necessitating further extensive research to validate the evidence in this field." (PMID 37841931, 2023). "In a cross-sectional study, the prevalence of asthma in CFTR heterozygotes was significantly higher (9%) than in non-carriers (6%), (p = 0.04)." (PMID 36983403, 2023). "The data suggest an upregulation of SLC26A9-dependent chloride secretion in asthma, but not in the presence of F508del-CFTR." (PMID 35328418, 2022). "In this study, we present the case of a female patient with features of asthma and mild or non-classic CF, who was referred for CFTR genetic analyses at our laboratory." (PMID 27996019, 2016). "This would suggest that hypertonic saline may be beneficial in other inflammatory lung diseases where there is functional CFTR, like COPD or asthma." (PMID 20799947, 2010). "Modulation of ENaC, CFTR, CaCC, KCNQ1 and KCNN4 ion channels by estrogen negatively affect airway surface liquid height and mucociliary clearance which impact on mucus production, bacterial virulence and airway inflammation, contributing to CF and asthma pathophysiology." (PMID 39026347, 2024). "Given the increasing evidence for an acquired CFTR dysfunction not only during HF but also in classic chronic lung diseases such as COPD and asthma, the indication that CFTR modulators may be useful therapeutics in the treatment of acquired CFTR abnormalities is certainly of interest to the field." (PMID 35967318, 2022). "However, this approach is also being applied to CFTR-dependent secretory diarrhoeas, and may be relevant to other disease in which a link to CFTR malfunction is emerging, such as acute pancreatitis, COPD and asthma." (PMID 27714410, 2017). "Most importantly, we showed that functional characteristics were maintained following conditional reprogramming specifically, CFTR function was lacking in CRAECs derived from children with CF and defective wound repair was maintained in CRAECs from children with asthma." (PMID 29269735, 2017).
cholera (35 papers, 2011 to 2024). "In this model, increased cAMP activates the cystic fibrosis transmembrane conductance regulator (CFTR) chloride channel, which leads to a loss of Cl−, Na+, and water in the intestinal lumen, causing the devastating diarrhea characteristic of cholera." (PMID 32092898, 2020). "CFTR is the primary route for Cl− secretion in secretory diarrheas caused by bacterial enterotoxins in cholera and Travelers' diarrhea (caused by enterotoxigenic E. coli)." (PMID 24551253, 2014). "The pivotal role of CFTR in the pathophysiology of cholera is corroborated by the observation that CFTR deficient animals are immune to the effects of CTX." (PMID 23935921, 2013). "Investigation of pathophysiological mechanisms underlying diarrhea in this new cholera model has highlighted CFTR as a therapeutic target for treatment of cholera." (PMID 23826402, 2013). "Cyclic nucleotide–mediated (cAMP- or cGMP-mediated) CFTR activation and consequent Cl– secretion represent the key pathology in certain secretory diarrheas including cholera, and traveler’s diarrhea and diarrhea caused by vasoactive intestinal peptide–secreting (VIP-secreting) tumors (VIPomas)." (PMID 37962961, 2024). "As opposed to the loss of function of CFTR in CF, the enterotoxins of Vibrio cholerae (producing cholera) and certain Escherichia coli strains (traveler’s diarrhea) hyperactivate CFTR causing secretory diarrhea characterized by enhanced salt and water loss in feces." (PMID 38213468, 2022). "CFTR inhibitors have been shown in model systems to rapidly block fluid loss during enterotoxin‐mediated diarrhoeas (e.g., cholera), and could be useful in preventing fatal dehydration and further disease spread." (PMID 33113586, 2020). "The activation of CFTR is thought to be one of the main causes of cholera-induced diarrhea." (PMID 31383845, 2019). "For example, the high frequency of the delta F508 mutation in CFTR has been hypothesized to be the result of a heterozygote advantage due to cholera resistance." (PMID 21901107, 2011). "High consanguinity would be a main driver for the high GCF observed in the cohort, with other cases may be attributable to balancing selection, as illustrated by HBB and CFTR in which variants are known to confer resistance against Malaria and Cholera, respectively." (PMID 38584274, 2024). "While this view of disease-causing Htt and CFTR alleles might initially seem counterintuitive, it should be remembered that the more common Htt alleles increase cancer susceptibility, while those of CFTR increase cholera susceptibility: they too are disease-promoting alleles." (PMID 39374830, 2024). "Interestingly, pre-miR-145-5p is a potent inhibitor of CFTR using the Caco-2 intestinal cell line; a model system to validate CFTR inhibitors for possible treatment of secretory diarrhea associated with cholera." (PMID 37104011, 2023). "Cholera and traveler’s diarrhea are major secretory diarrheas caused by the bacterial enterotoxins cholera toxin and heat-stable E. coli enterotoxin, respectively, whose mechanism involves activation of enterocyte CFTR by phosphorylation following elevation of intracellular cyclic nucleotides." (PMID 33400691, 2021). "Cholera is a severe form of secretory diarrhea, in which the key pathology is increased CFTR-mediated Cl– secretion and reduced NHE3-mediated Na+ absorption due to elevated cAMP levels in intestinal epithelial cells." (PMID 37962961, 2024). "Although elevation of cAMP — and hence CFTR activation — is the key mechanism in cholera, in certain secretory diarrheas, elevation of intracellular Ca2+ is the major driver of Cl– secretion via Ca2+-activated Cl– channels (CaCCs)." (PMID 37962961, 2024). "The usefulness and antidiarrheal efficacy of CFTR inhibitors have been validated on human intestinal epithelial cells and in mouse models of cholera." (PMID 37104011, 2023).